BDNF (brain derived neurotrophic factor)
Diseases named in the same sentence as BDNF in open-access papers (continued):
Sharing a sentence is not in itself a finding about the gene and the disease.
Cerebral ischemia (206 papers, 2009 to 2026). Restriction of arterial blood supply to the brain associated with insufficient oxygenation to support the metabolic requirements of the tissue. "BDNF is a neurotrophic factor, and studies have demonstrated that its upregulation is linked to enhanced neurogenesis following cerebral ischemia." (PMID 40869376, 2025). "Rutin also attenuates neuronal loss in cerebral ischemia/reperfusion injury rats through estrogen receptor-mediated BDNF-TrκB and NGF-TrκA signaling pathways." (PMID 39877393, 2024). "Both nimodipine and Tdv demonstrated a reduction in cerebral infarct size and improvement in neurological impairment following cerebral ischemia, which was associated with inhibition of neuronal apoptosis and promotion of BDNF expression." (PMID 37153779, 2023). "Pyridoxine deficiency and/or brain ischemia decreased BDNF levels in the hippocampus, and BDNF levels were lowest in PDD-fed ischemic gerbils." (PMID 32759679, 2020). "The BDNF signaling pathway is closely associated with cerebral ischemia and neurogenesis and plays important roles in supporting neuronal survival and maintenance." (PMID 28824455, 2017). "To explore the underlying mechanisms of EA preconditioning on focal cerebral ischemia, we investigated BDNF and SDF-1α expression in the ischemic cortex." (PMID 23356671, 2013). "Taken together, these findings suggest that functional recovery in cerebral ischemia is associated with not only BDNF or NGF, but it can also be mediated by NT-4 and other tyrosine kinase receptors." (PMID 23526925, 2013). "BDNF is mainly expressed in the hippocampus and cortex, and increasing the levels of BDNF to promote neuroregeneration is an important mechanism associated with the improvement of neurological function, after the onset of cerebral ischemia." (PMID 35317197, 2022). "Therefore, we evaluated salivary metabolic profiles associated with altered hippocampal BDNF expression levels in a cerebral ischemia mouse model using metabolomic analyses." (PMID 33920851, 2021). "Additionally, it upregulates the expression of growth-associated protein 43 and brain-derived neurotrophic factor following cerebral ischemia-reperfusion, thereby promoting neural regeneration, improving neuronal function, and mitigating cerebral ischemia/reperfusion injury in a rat model." (PMID 39792753, 2025). "In addition, the protective effects of simvastatin may also be related to its ability to diminish brain ischemia, prevent cholinergic neuronal loss, modulate brain-derived neurotrophic factor expression, and promote nitric oxide synthesis." (PMID 34306309, 2021). "In summary, these data suggest that in cerebral ischemia, synaptic loss is caused primarily by microglial activation-mediated synaptic phagocytosis by signaling pathways such as MEGF10 and BDNF." (PMID 40313098, 2026). "These pharmacological agents significantly upregulate the expression of VEGF and BDNF, and synergistically promoting angiogenesis and neurogenesis after cerebral ischemia." (PMID 40949877, 2025). "After cerebral ischemia, the expression of BDNF and VEGF in brain tissue increases, promoting endogenous NSC proliferation." (PMID 40949877, 2025). "Previous studies have demonstrated that acupuncture enhances BDNF expression in animal models of focal cerebral ischemia, promoting dendritic spine regeneration and facilitating brain tissue repair." (PMID 41458115, 2025). "Ruyi Zhenbao pill aids neurological recovery following cerebral ischemia/reperfusion by stimulating neurogenesis and angiogenesis, primarily through the upregulation of BDNF, NGF, and VEGF." (PMID 40520194, 2025). "BDNF plays an important role in promoting neural regeneration, regulating synaptic plasticity and functional recovery from cerebral ischemia." (PMID 39090706, 2024).
Cerebral ischemia (continued). "Here, it was aimed to investigate the effects of intracerebroventricular (ICV) Brain Derived Neurotrophic Factor (BDNF) infusion for 7 days following cerebral ischemia (CI) on autophagy in neurons in the penumbra." (PMID 38520223, 2024). "In an in vitro study, DEX-mediated neuroprotective effects in a cerebral ischemia model were shown to be accompanied by the attenuation of inflammation and oxidative stress and increased BDNF expression." (PMID 39768379, 2024). "The relationship between Notch pathway and BDNF after cerebral ischemia and the role of salidroside still need to be further explored." (PMID 39090706, 2024). "It has been shown that BDNF levels are significantly low in the serum of rats with cerebral ischemia." (PMID 39749196, 2024). "In ischemic brain injury, BDNF responses depend largely on both the nature of injury (global cerebral ischemia following cardiac arrest vs. focal ischemia in pediatric stroke) and age." (PMID 38397427, 2024). "Previous studies show that OEA treatment restores BDNF following cerebral ischemia or after stress exposure." (PMID 39201687, 2024). "After cerebral ischemia, miR-199a-5p regulates Cav-1 expression, leading to increased expression of BDNF and VEGF, promoting neural stem cell differentiation and endogenous neurogenesis." (PMID 38922036, 2024). "However, after brain ischemia injury occurs it causes a decrease in the level of BDNF which results in changes in the ability of neuroplasticity or repair of nerve cell function, spontaneously or by inducing rehabilitation BDNF is an important molecule in brain plasticity." (PMID 39810851, 2024). "On the other hand, activated CREBs also play a neuroprotective role through upregulation of brain derived neurotrophic factor (BDNF) and anti-inflammatory factors in animal model of cerebral ischemia." (PMID 36843941, 2023). "The suppression of CREB pathway inhibited the expression of BDNF and Bcl-2, which affected neuronal survival after cerebral ischemia." (PMID 37153779, 2023). "Our results have proven that CREB-mediated sig+naling pathways are involved in the effect of Tdv on apoptosis and of BDNF in the progression of cerebral ischemia." (PMID 37153779, 2023). "In a study conducted on a rat model of cerebral ischemia, treatment with BDNF significantly reduced infarct size and neuronal cell death." (PMID 37106754, 2023). "Microglia activated after cerebral ischemia secrete more BDNF, which binds to its high-affinity receptor TrkB to protect during the acute stroke and stimulate neural repair at a later stage." (PMID 37780709, 2023). "Microglia activated after cerebral ischemia secrete more BDNF, which exerts its effects through binding to its high-affinity receptor TrkB." (PMID 37780709, 2023). "For example, Yang and colleagues have shown that BER can exert neuroprotective effects in rats that have suffered cerebral ischemia by reducing the rate of apoptosis by the BDNF-TrkB- PI3K/Akt pathway." (PMID 36594063, 2023). "It has been shown that acupuncture can upregulate the expression of endogenous BDNF and stem cell factors in areas such as the cerebral cortex, hippocampus, and caudate cone after cerebral ischemia, which facilitates the repair of neuronal damage." (PMID 37780709, 2023). "Several studies have demonstrated that RIPostC after cerebral ischemia protected against degenerative events in rats via increased BDNF expression." (PMID 36750711, 2023). "For instance, HMF showed neuroprotection against brain ischemia by inducing BDNF production and anti-inflammatory actions and demonstrated an immunomodulatory function for the reduction of interleukin-4 expression in CD3/CD28-stimulated spleen cells in mice." (PMID 37180721, 2023). "WBV was shown to increase BDNF levels in the peri-infarct regions after brain ischemia-reperfusion in middle-aged female rats." (PMID 36960421, 2023).
Cerebral ischemia (continued). "ME-induced cerebral ischemia led to an obvious downregulation of BDNF protein level in the serum compared with sham group, whereas administration with 15, 30, 60, 120, and 240 mg/kg PNS for 14 days all attenuated ME-induced decrease of BDNF content." (PMID 35770087, 2022). "In recent years, neurotrophic factors such as nerve growth factor, brain-derived neurotrophic factor, and neurotrophin have been used to treat neurodegenerative diseases, including cerebral ischemia." (PMID 34773698, 2022). "In the striatum, relative expression of GDNF and VEGF remarkably down-regulated following cerebral ischemia; while expression of NT-3 and BDNF was increased more than 600 and 200%, respectively." (PMID 35879657, 2022). "As we previously found, crocin can significantly promote the secretion of BDNF in the hippocampus of rats with cerebral ischemia." (PMID 35431921, 2022). "More and more studies have revealed that BDNF can upregulate and exert neuroprotective effects in cerebral ischemia." (PMID 35431946, 2022). "Rutin mitigates cerebral ischemia injury by activating estrogen receptor-mediated BDNF-TrkB/NGF-TrkA signaling, and chlorogenic acid mitigates ischemic injury by increasing the level of NGF in brain tissue." (PMID 35833035, 2022). "Similar to a previous study, our model mice showed decreased blood BDNF levels due to cerebral ischemia." (PMID 33920851, 2021). "The coresearchers revealed that the re-expression of miR-130a enhanced the activation of BDNF-mediated PI3K/Akt signaling pathway by inhibiting PTEN, a mechanism that underlies the neuroprotection against cerebral ischemia–reperfusion injury." (PMID 35002691, 2021). "BDNF has also been demonstrated to provide a neuroprotective effect under injurious conditions, such as glutamatergic stimulation, cerebral ischemia, hypoglycemia, and neurotoxicity." (PMID 33920974, 2021). "Apart from that, brain derived neurotrophic factor (BDNF) can help alleviate cerebral ischemia injury by interfering with apoptotic channels." (PMID 35095491, 2021). "In particular, a previous study indicated that treatment with BCL remarkably promoted the expression of BDNF in a global cerebral ischemia/reperfusion injury model." (PMID 34234667, 2021). "In the case of cerebral ischemia and hypoxia, BDNF can protect brain cells via inhibiting apoptosis." (PMID 33413076, 2021). "l-borneol promotes angiogenesis and neurogenesis by increasing the levels of Ang 1, VEGF and BDNF after cerebral ischemia." (PMID 33746762, 2021). "We investigated the impact of cerebral ischemia on the BDNF-related pathway in the hippocampus, focusing on GAD1, which is a GABA-associated factor." (PMID 33920851, 2021). "Macrophage migration inhibitory factor (MIF) exerts neuroprotective effects against cerebral ischemia/reperfusion injury by inhibiting neuronal apoptosis and inducing the expression of brain-derived neurotrophic factor (BDNF)." (PMID 33672416, 2021). "Several studies have revealed that Rb1 regulates the expression of BDNF and activates neurogenesis in rats with experimental cerebral ischemia." (PMID 34658847, 2021). "Conjugated brain-derived neurotrophic factor (BDNF) to a monoclonal antibody against TFR demonstrated nearly 70% neuroprotection in focal brain ischemia after intravenous injection of conjugated BDNF." (PMID 33633672, 2021). "It is known that the expression of BDNF and TrkA receptors in hippocampal neurons decreases after cerebral ischemia, but the expression of TrkB receptors increases." (PMID 32219700, 2020). "Becker holds that when cerebral ischemia occurs, brain-derived neurotrophic factor binds to the neurotrophin receptor p75 and then activates the c-JunN-terminal kinase pathway to mediate apoptosis." (PMID 32714405, 2020). "In summary, our study has evidenced that combined pretreatment with TP and Ki20227 modulates BDNF-Akt and autophagy pathways and confers protectiveness against cerebral ischemia." (PMID 33192177, 2020).
Cerebral ischemia (continued). "Earlier, it was reported that genetic manipulation of BM‐MSCs that led to over‐expression of BDNF ameliorate the devastating conditions of cerebral ischemia." (PMID 32281225, 2020). "Elevated levels of butyrate in the brain have been linked with neuroprotective effects against vascular dementia and cerebral ischemia in mice and rats, via an increasing brain-derived neurotrophic factor." (PMID 32344633, 2020). "Conversely, attenuation of brain BDNF levels or effects following cerebral ischemia results in reduced neuroplastic changes or decreased recovery of function, both in spontaneous and in rehabilitation-induced recovery scenarios." (PMID 33275615, 2020). "Both animal and clinical studies have shown that BDNF has an effect to improve neurological recovery, prevent neuronal death, and support the survival of many types of neurons after cerebral ischemia." (PMID 30581534, 2018). "Our findings are further supported in other models of neuronal injury such as cerebral ischemia, in which the loss of CCR5 reduces long-term inflammatory injury, potentially through increases in BDNF levels." (PMID 30305110, 2018). "In cerebral ischemia rat model and multiple sclerosis rats and mice models, iridoid glycosides also enhanced the levels of brain-derived neurotrophic factor and nerve growth factor." (PMID 29983732, 2018). "As one of the main neurotrophic factors, BDNF constitutes a promising remedy for reducing neuronal injury after cerebral ischemia and for functional recovery in ALS." (PMID 29179434, 2017). "BDNF has been shown to reduce infarct size and improve functional outcome following cerebral ischemia." (PMID 28640888, 2017). "Although neurogenesis is coordinately regulated by several factors, our findings imply that an IGF-1- and/or BDNF-independent PI3-K/Akt/GSK-3β pathway was enhanced by cerebral ischemia." (PMID 27866373, 2017). "At 24 hours after cerebral ischemia, candesartan significantly increased BDNF expression in the contralesional hemisphere when compared to saline treated animals." (PMID 28640888, 2017). "It was also reported that an increase in BDNF mRNA expression occurs between 1 and 3 days, returning to basal level 4 days after cerebral ischemia." (PMID 28056920, 2017). "Previously, it has been demonstrated that intravenous administration of BDNF reduces the infarct size following brain ischemia." (PMID 28202057, 2017). "Basal endogenous BDNF/trkB expression increased within both hemispheres following moderate cerebral ischemia (including the penumbra) during the first 2 weeks but motor recovery remains widely insufficient." (PMID 26682073, 2015). "Recently, our study has reported that rat brain ischemia stimulated the expression of Gadd45b in the cortex, Gadd45b-RNAi significantly decreased the level of BDNF and inhibited axonal plasticity after MCAO." (PMID 26698301, 2015). "Such properties of the BDNF have been reported in other neuropathological conditions, such as brain ischemia and after the partial dorsal rhizotomy." (PMID 25947167, 2015). "A supportive role for microglia in brain neuroplasticity stimulation possibly through BDNF production has been described in an animal model of brain ischemia." (PMID 26252217, 2015). "In a study of rodent cerebral ischemia, intra-arterial injection of microglia prevented the ischemia-induced decline of brain-derived neurotrophic factor (BDNF) in hippocampus and offered neuroprotection." (PMID 25642419, 2014). "Previous studies have also reported that pharmacological activators of the ERK1/2 signaling pathway elicit neuroprotection through the upregulation of BDNF expression in cerebral ischemia models." (PMID 24606810, 2014). "The neuroprotective role of BDNF has been shown in ischemic injury including focal brain ischemia, hypoxic-ischemia and global brain ischemia induced by four vessels occlusions." (PMID 25671079, 2014).
Cerebral ischemia (continued). "The present study showed that EA stimulation at the GV20 and GV14 acupoints before focal cerebral ischemia has neuroprotective potential mediated, at least in part, by increased BDNF and SDF-1α expression." (PMID 23356671, 2013). "Conversely decreasing BDNF levels or attenuating its effects following cerebral ischemia diminishes recovery of function." (PMID 21949858, 2011). "It is important to know which rehabilitation intervention is more effective in facilitating motor recovery and up-regulating brain neurotrophic factor (BDNF) which is a leading factor in learning and memory, after brain ischemia." (PMID 21347437, 2011). "For example, MSCs genetically modified with the BDNF gene effectively promote axonal regeneration in transected adult rat spinal cord and also protect against injury in a cerebral ischemia model in adult rats." (PMID 20462460, 2010). "On the other hand, one possible mechanism underlying brain ischemia-induced proliferation of neural progenitors is stimulation of tyrosine kinase-coupled receptors by induction of growth factors such as FGF, BDNF and NGF." (PMID 19943942, 2009). "Testosterone increased BDNF levels and neurogenesis after focal cerebral ischemia." (PMID 40141172, 2025). "CIGs mitigate neuroinflammation in autoimmune encephalitis and traumatic brain injury by inhibiting the JAK/STAT and NF-κB/STAT3 pathways, while protecting against white matter lesions in rat models of cerebral ischemia through activation of the BDNF/Neuregulin-1 pathway." (PMID 41403435, 2025). "For instance, Zhong demonstrated in a rat model of cerebral ischemia that the combination of electroacupuncture and low-frequency rTMS significantly enhanced BDNF expression and promoted synaptic plasticity in the hippocampus, outperforming either intervention alone." (PMID 41458115, 2025). "Like TBI, evidence suggests therapeutic effects of BDNF in adult models of cerebral ischemia." (PMID 38397427, 2024). "A1 astrocytes-secreted IL-1β, IL-6, IL-18 and TNF-α aggravate the neuroinflammation and deteriorate the brain tissue damage.Whereas, A2 astrocytes produce brain-derived neurotrophic factor (BDNF), which is known as neurotrophic factor and provide neuroprotection against cerebral ischemia injury." (PMID 38421829, 2024). "Shi demonstrated that chrysin could play a neuroprotective role in cerebral ischemia–reperfusion injury by upregulating the expression of brain-derived neurotrophic factor (BDNF) and nerve growth factor (NGF)." (PMID 39202984, 2024). "Moreover, long-term iTBS has been found to promote neural structural and functional recovery by enhancing neurogenesis and migration through the miR-551b-5p/BDNF/TrkB pathway in cerebral ischemia–reperfusion injury models." (PMID 38725649, 2024). "BDNF, widely expressed in the central nervous system, gut and other tissues, combines with tropomyosin receptor kinase B to play a neuroprotective role in conditions such as neurotoxicity and cerebral ischemia." (PMID 39075604, 2024). "Since BDNF supports the differentiation, proliferation, and survival of neurons in the brain in many severe conditions, including cerebral ischemia and neurotoxicity, it is important to understand how the BDNF protein is stimulated or maintained for normal physiological conditions in the brain." (PMID 39194500, 2024). "In addition, in bad conditions, BDNF can show neuroprotective effects in the form of glutamatergic stimulation, hypoglycemia, cerebral ischemia, and neurotoxicity." (PMID 39810851, 2024). "By increasing the expression of KCC2 and BDNF in the perilesional cortex and enhancing synaptic plasticity in the denervated cervical spinal cord after cerebral ischemia, the total length of CST fibers sprouting into the denervated cervical spinal cord significantly increased after stroke." (PMID 37704780, 2024).